CASP1 (caspase 1)
Diseases named in the same sentence as CASP1 in open-access papers (continued):
Sharing a sentence is not in itself a finding about the gene and the disease.
Sepsis (continued). "Recent studies suggest that EV caspase-1 activity can induce EC injury and that sepsis-induced pyroptosis of monocytes and ECs can release caspase-1 containing EVs." (PMID 37180111, 2023). "Numerous studies have shown that the factors involved in the NLPR3/Caspase-1/GSDMD process, a classical pathway associated with pyroptosis, are highly expressed in patients and animals with sepsis." (PMID 37939116, 2023). "We also found that caspase-1 induced pyroptosis and inflammation in sepsis-induced AKI in this study." (PMID 37256132, 2023). "Activation of the TGF-β/NLRP3/caspase-1 signaling pathway stimulates pyroptosis, which ultimately exacerbates sepsis-induced acute kidney injury." (PMID 38102696, 2023). "At days 1 and 7 after sepsis, blocking caspase-1 resulted in reduced levels of IL-1β, monocyte chemoattractant protein-1, and TNF-α in both the bloodstream and the brain." (PMID 37891821, 2023). "Given that the caspase-1 inhibitor has been shown to improve sepsis-related nuclear autophagy, we conducted a further analysis of the brain ultrastructure using a TEM." (PMID 36979288, 2023). "Mangiferin, a flavonoid widely distributed in several herbs, inhibited NLRP3/caspase-1/-11-mediated GSDMD activation in sepsis." (PMID 38022612, 2023). "To explore the relationship between EV content and sepsis outcomes, we determined caspase-1 activity in total circulating EVs from healthy controls and septic patients and analyzed its association with sepsis outcomes including mortality, ARDS and ARF." (PMID 37180111, 2023). "In vivo, the recombinant A-box, but also caspase-1 cleavage of HMGB1 have been shown to be protective against sepsis, a property depending on RAGE." (PMID 37180096, 2023). "However, circulating EV caspase-1 and its association with sepsis outcomes remains largely unknown." (PMID 37180111, 2023). "To explore the relationship between cell-specific EV content and sepsis outcomes, we examined caspase-1 activity in circulating monocyte-derived EVs." (PMID 37180111, 2023). "Based on the results obtained in the current study, a conclusion is reached that YTHDF1 promotes NLRP3 ubiquitination by upregulating WWP1, thereby inhibiting caspase-1-dependent pyroptosis, which contributes to attenuation of sepsis." (PMID 35508474, 2022). "The inflammasome component NLRP3 is upregulated in sepsis which leads to the cleavage of pro-caspase-1 to caspase-1, and subsequently maturation and release of the proinflammatory cytokine, IL-1β." (PMID 35774785, 2022). "In order to further investigate the effect of YTHDF1/WWP1/NLRP3/caspase-1 axis on sepsis, RAW264.7 cells were transfected with oe-NC/oe-YTHDF1, or sh-NC/sh-WWP1." (PMID 35508474, 2022). "As expected, the expression of mm-il1b and mm-il6 during sepsis was reduced in the Casp1/11-/- mice." (PMID 34996441, 2022). "Consistently, Caspase-1 activation was more evident in macrophages from Card9−/−-sepsis mice compared with those from WT-sepsis mice." (PMID 35618701, 2022). "In a caecal ligation puncture model (sepsis-induced AKI), NLRP3 deficiency and caspase-1 suppression reduced kidney injury, inflammation, and caspase-1 activation." (PMID 35204131, 2022). "The present study intends to investigate the regulatory network and function of the microarray-predicted YTHDF1 in caspase-1-dependent pyroptosis of sepsis." (PMID 35508474, 2022). "Currently, the treatment strategies of inhibiting the caspase-1 signaling pathway and the caspase-11 pathway have been confirmed effectively in several sepsis models." (PMID 36032662, 2022). "Treated with MCC950 (the NLRP3 inhibitor) or Ac-YVAD-CMK (the Caspase-1 inhibitor) prevented sepsis-induced neuronal damage and cognitive deficits." (PMID 36171629, 2022). "In the current study, Western blot results showed that hippocampal NLRP3, procaspase-1, and cleaved caspase-1 were upregulated in the sepsis brain injury mice." (PMID 35571246, 2022).
Sepsis (continued). "The pathogen-associated molecular patterns and damage-associated molecular patterns in sepsis activate NLRP3 and caspase-1 to release inflammatory cytokines such as IL-18 and IL-1β, aggravating the inflammatory response." (PMID 36032662, 2022). "Mechanistically, our study further demonstrated that WWP1 suppressed caspase-1-dependent pyroptosis by promoting NLRP3 ubiquitination in sepsis." (PMID 35508474, 2022). "The results showed that the levels of caspase-11, GSDMD-NT, NLRP3, ASC, caspase-1, IL-1β, and IL-18 were increased in sepsis mice and that ST pre-treatment suppressed this effect." (PMID 34483936, 2021). "To further confirm the effect of CASP-1 inflammasome activation during sepsis, we examined changes in the DCs pyroptosis rates." (PMID 34741186, 2021). "In contrast, Pad4 depletion in the macrophages can increase Caspase-1 mediated pyroptosis in the mouse model of PA-sepsis." (PMID 34804050, 2021). "Overall, these results revealed that SESN2 suppresses CHOP-mediated activation of NLRP3/CASP-1-dependent pyroptosis during sepsis." (PMID 34741186, 2021). "Previous reports also showed that group 2 innate lymphoid cell-derived IL-9 reduces mouse lung endothelial cell (MLEC) pyroptosis in sepsis through attenuating caspase-1 activation in MLECs." (PMID 34992715, 2021). "We demonstrated a marked renoprotective effect of caspase-1-inhibitor AC-YVAD-CMK in a rat model of sepsis by inhibition of pyroptosis." (PMID 34222479, 2021). "One study reported EVs carrying caspase-1 in the plasma of sepsis patients, which were able to induce apoptosis in healthy lymphocytes in vitro." (PMID 34451925, 2021). "Neutralization of CitH3 with a monoclonal antibody in the CLP-induced sepsis model improves survival and attenuates acute lung injury as well as pro-Caspase-1 cleavage in the lung tissue." (PMID 34950139, 2021). "In our previous study, we have found that dihydromyricetin ameliorates sepsis-stimulated acute lung injury through blocking NLRP3/caspase-1 signaling in mice models." (PMID 34992715, 2021). "One study reported that the caspase-1 inhibitor VX-765 reduced caspase-1 expression in the brain tissue of the sepsis mouse model and reduce the production of mature IL-1β, which inhibited pyroptosis and eventually attenuated the inflammatory response." (PMID 34305952, 2021). "VX765, a specific caspase-1 inhibitor, has been shown to have a protective effect against several diseases including sepsis, atherosclerosis, and glial inflammatory disease." (PMID 34977239, 2021). "The findings of this study showed that pretreatment with GLN increased liver caspase-11 and NLRP3 gene expressions at 24 h, while caspase-1/11 and GadD protein levels were downregulated at 72 h after sepsis." (PMID 32295272, 2020). "It is important to note that caspase-1 genetic deletion leads to suppressed IL-1β levels and confers a protective effect on murine sepsis models and improves the survival of mice." (PMID 32825174, 2020). "Their research also depicted that the FXR-bile acid axis involves in the regulation of cholestasis-associated sepsis, which can be mediated by the negative regulation of NLRP3 inflammasome via the direct binding of FXR to NLRP3 and caspase 1 in macrophages." (PMID 32660430, 2020). "High expression of caspase-1 was confirmed using immunohistochemistry in spleens from sepsis patients." (PMID 33324236, 2020). "Caspase-1 was shown to predict the outcome of sepsis, in that high caspase-1 activation during the first day of sepsis correlated with poor sepsis outcome." (PMID 33613537, 2020). "Caspase-1 has been shown to promote splenic B cell apoptosis and lymphocyte apoptosis during sepsis." (PMID 33324236, 2020). "Although ROS and NLRP3/caspase-1-induced apoptosis in sepsis have been studied, future experiments are needed to show more evidence for their cooperation or interaction." (PMID 33324236, 2020).
Sepsis (continued). "When comparing the sepsis groups at 72 h, the Sepsis-G group had lower expression levels of caspase-1 and caspase-11." (PMID 32295272, 2020). "Pyroptosis is a caspase-1-dependent cell death, and is considered to play a crucial role in the dysregulation of inflammatory/immune responses in sepsis." (PMID 30911553, 2019). "Unlike TNF-α, whose synthesis and secretion are inflammasome-independent, production of IL-1β and IL-18, which requires inflammasome-dependent caspase-1 activation, was more abundant in the serum of Dox-induced iUVRAGFS mice than littermate control in sepsis." (PMID 31831743, 2019). "While little information about this exists, our data show that sepsis-triggered canonical inflammasome depends on the NLRP3/caspase-1 pathway for the maturation and secretion of IL-1β and on GSDMD for the induction of pyroptosis." (PMID 30276509, 2019). "Active NLRP3 promotes the secretion of the cytokines IL-1β and the cysteine proteases (caspase-1), which are considered protective during initial process of sepsis." (PMID 30779706, 2019). "The death of Caspase-1−/− MLEC was reduced by ~70%, as compared with WT MLEC, indicating that caspase-1-dependent pyroptosis serves as a major form of MLEC death following sepsis." (PMID 29511181, 2018). "In this study, by using a mouse sepsis model, we identified a novel mechanism by which NETs induce macrophage (Mφ) pyroptosis, a caspase-1-dependent regulated cell death." (PMID 29789550, 2018). "ILC2-derived IL-9, as shown in the data, through attenuating caspase-1 activation in MLEC reduces MLEC pyroptosis in sepsis." (PMID 29511181, 2018). "Expansion of ILC2 in the lungs provides ILC2-derived IL-9 in the lungs, which reduces sepsis-induced EC pyroptosis through suppressing caspase-1 activation." (PMID 29511181, 2018). "Shikonin inhibited EIF2AK2 phosphorylation and caspase-1 activity in PMs obtained from mice subjected to lethal endotoxemia or polymicrobial sepsis." (PMID 27779186, 2016). "We detected that sepsis stimulates an over 2-fold increase in accumulation of the active form of caspase 1, resulting in a nearly 2000-fold induction of IL–1β generation, and Mito-Vit-E profoundly suppressed both events." (PMID 26448624, 2015). "Both Mito-Vit-E and TLR9 inhibitor OND-I repressed LPS-induced up-regulation of MYD88, RAGE, ASC, activated caspase 1 and IL–1β, confirming that sepsis induces a mtROS dependent mtDNA-TLR9 pathway in cardiomyocytes." (PMID 26448624, 2015). "The findings suggest that microparticulate caspase-1 released during sepsis is important in the host response to sepsis, at least in part, via its ability to induce apoptosis." (PMID 26710067, 2015). "In our own published work, we have demonstrated the novel role of caspase-1 in lymphocyte apoptosis and sepsis survival and smooth muscle cells apoptosis in atherosclerosis." (PMID 26710067, 2015). "The human inflammatory caspases, including caspase-1, -4, -5 and -12, are considered as key regulators of innate immunity protecting from sepsis and numerous inflammatory diseases." (PMID 26158519, 2015). "Our own work specifically showed that pharmacologic blockade of caspase-1 activity reduced splenocyte cell death in murine sepsis." (PMID 24643116, 2014). "Salient features of this the NLP3 inflammasome/ caspase-1 pathway were confirmed in in vivo models of endotoxemia/sepsis." (PMID 25216263, 2014). "We sought to determine if MVs containing caspase-1 are being released into the blood during human sepsis and induce apoptosis.." (PMID 24643116, 2014). "The inflammasome, a molecular complex which includes caspase-1, is essential to the innate immune response to infection and also important in sepsis induced apoptosis." (PMID 24643116, 2014). "Although these isolated observations support a potential role for the NLRP3 inflammasome/caspase-1/IL-1β pathway, the present study is the first to provide a systematic assessment of this pathway in endotoxemia/sepsis both in vivo and in vitro." (PMID 25216263, 2014).
Sepsis (continued). "Work from our own laboratory has shown the unique role of caspase-1 in regulating sepsis survival by regulating splenic lymphocyte apoptosis." (PMID 24643116, 2014). "Further, we show that blockade of the NLRP3 inflammasome/caspase-1/IL-1β pathway can afford protection against lethality in a model of polymicrobial sepsis." (PMID 25216263, 2014). "Since caspase-1 has a role in both inflammatory cytokine processing and apoptosis, understanding its regulation is essential to understanding sepsis." (PMID 24643116, 2014). "Although our findings strongly support a role for the NLRP3 inflammasome/caspase-1/ IL-1β pathway of CFs in the myocardial dysfunction, as well as, lethality in sepsis, extrapolation to the human condition is rather tenuous." (PMID 25216263, 2014). "Previous investigations have demonstrated that pharmacologic blockade of caspase-1 improves organ function, reduces lymphocyte apoptosis and increases survival in animal models of sepsis." (PMID 24643116, 2014). "The present study was designed to expand upon this observation by analyzing the role of microvesicular caspase-1 in an ex vivo study of plasma microparticles released during human sepsis." (PMID 24643116, 2014). "To this end, we investigated the down regulation of IL-1β in sepsis and experimental endotoxemia in human volunteers with emphasis on the activation of caspase-1 and subsequent IL-1β production." (PMID 21244670, 2011). "We investigated inflammasome activation and found that in patients with sepsis, both pro-caspase-1 and activated caspase-1 were markedly decreased." (PMID 21244670, 2011). "The impact of a potential anti-inflammatory component through inhibition of caspase-1 is difficult to predict in the context of sepsis." (PMID 19740426, 2009). "Work from our own laboratory has shown the unique role of caspase-1 in regulating sepsis survival by regulating lymphocyte apoptosis." (PMID 19779610, 2009). "While a significant increase in the mean fold-change in intracellular caspase-1 levels in the C19wSepsis (> 4-fold increase, **p=0.0021) and Sepsis Alone cohorts (> 4-fold increase, ****p<0.0001) were observed compared to healthy controls, C19NoSepsis cohort showed no significant change (p>0.05)." (PMID 40051620, 2025). "CASP1 upregulation might be advantageous in sepsis, and our RNA-seq analysis revealed that CASP1 was primarily located in the macrophage lineage." (PMID 40258762, 2025). "Our research results demonstrate that ECG alleviates sepsis-induced ALI by inhibiting the NLRP3/Caspase-1/GSDMD signaling pathway-mediated pyroptosis, the Bcl-2/Bax/Caspase-3 signaling pathway-mediated apoptosis, and regulating the ZBP1/MLKL/RIPK1 signaling pathway-mediated necroptosis." (PMID 41496909, 2025). "Our findings indicated that ECDD-S16, a novel compound, interferes with caspase-1/4/5 activation, which may lead to the prevention of sepsis in acute melioidosis patients." (PMID 40627773, 2025). "In addition, phospholipase D2 (PLD2) deletion ameliorates sepsis-induced cardiomyopathy by suppressing cardiomyocyte pyroptosis via the NLRP3/caspase-1/GSDMD pathway." (PMID 40708650, 2025). "The analysis of immunofluorescence images and tissue-specific expression data revealed the different expression patterns of ADAM17, MGMT, CD81, and CASP1 at the cellular level and tissue level, which lays the foundation for further investigation of their roles in sepsis." (PMID 40258762, 2025). "Caspase-1 was a highly accurate indicator of sepsis (area under the ROC=0.7080)." (PMID 38410714, 2024). "Indeed, we and others have reported that CLP-sepsis causes both the activation of NLRP3 inflammasome and proteolytic cleavage of pro-caspase-1 to its active form caspase-1, finally leading to IL-1β maturation and release." (PMID 39559354, 2024). "Caspase-1-induced monocyte pyroptosis has also been noted in patients with post-traumatic sepsis." (PMID 39720718, 2024).
Sepsis (continued). "Indeed, caspase-1 was also significantly elevated in both ICU groups compared to healthy controls with overall levels being highest in the ICU-sepsis patients." (PMID 38410714, 2024). "Together, these results suggest that the combination of Aβx-40 and caspase-1 might be useful to predict sepsis and attendant organ injury." (PMID 38410714, 2024). "Thus, our discovery that Aβx-40 and caspase-1 are coordinately elevated during sepsis suggests their potential to impact other neurocognitive-related disease processes." (PMID 38410714, 2024). "TSP-1 deficiency protects mice against sepsis-induced AKI by decreasing the expression of inflammatory and apoptosis-promoting cytokines, such as the NLRP3 inflammasome, caspase-1, IL-1β, and IL-18, which increase cell viability and partially reverse cell pyroptosis." (PMID 38516004, 2024). "Furthermore, these investigations have revealed that PAD2 knockout in macrophages reduces Caspase-1 mediated pyroptosis in PA-induced sepsis, whereas PAD4 depletion in macrophages increases Caspase-1 mediated pyroptosis in the same mouse model 18,19." (PMID 39430255, 2024). "Importantly, caspase-1 has demonstrated a correlation with sepsis severity, where high caspase-1 activation in the first 24 h of sepsis is associated with increased mortality." (PMID 38921759, 2024). "Broad-spectrum caspase inhibitors could also be evaluated, such as VX-166, which is active against caspase-1, caspase-3 and caspase-7, and has been proposed for the treatment of sepsis and endotoxic shock." (PMID 39376663, 2024). "Studies have shown that IMD could reduce the expression of major inflammatory factors in sepsis by regulating the NLRP3/Caspase-1/IL-1β pathway, thereby exerting a protective effect against sepsis-induced cardiac dysfunction." (PMID 37745233, 2023). "Caspase-1, a member of the cysteinyl proteases family, plays a critical role in regulating inflammatory responses, apoptosis, and pyroptosis, three known features of sepsis." (PMID 37180111, 2023). "It has been reported that inactivation of NLRP3 inflammasomes and inhibition of caspase-1-mediated cleavage of GSDMD could prevent pyroptosis in LPS-induced sepsis in a mouse model, thereby alleviating the septic shock." (PMID 35508474, 2022). "Furthermore, genetic deficiency of NLRP3 or caspase-1 abrogated the high mortality and disrupted liver interendothelial junctions caused by high dose of HNP-1 during sepsis." (PMID 35935811, 2022). "To clarify whether Mito-TEMPO alleviates sepsis-induced liver damage by regulating caspase-1 expression and pyroptosis, we detected the protein and mRNA levels of pyroptosis-related proteins in the liver." (PMID 35769207, 2022). "This study clarified the regulatory role of YTHDF1 in sepsis with the involvement of WWP1/NLRP3/caspase-1 axis and found that YTHDF1 could upregulate WWP1 to enhance NLRP3 ubiquitination and restrict caspase-1-dependent pyroptosis in sepsis." (PMID 35508474, 2022). "NET-derived HMGB1 activates caspase-1-dependent macrophage pyroptosis during sepsis." (PMID 36430491, 2022). "Of note, neutralization of caspase-1-activated cytokines IL-1β/18 failed to achieve the protective effect of caspase-1 deficiency against sepsis and renal failure, suggesting that caspase-1 has other roles in disease besides activating cytokines effect." (PMID 36189207, 2022). "Shikonin also prevented the activation of the NLRP3/caspase-1/IL-1β inflammasome pathway and increased the survival rate of Balb/c mice with LPS-induced lethal endotoxemia and caecal ligation and puncture–induced sepsis." (PMID 35637461, 2022). "Previous studies have shown that monocyte-derived plasma EV containing gasdermin D and activated caspase-1 are more abundant in patients with sepsis-related ARDS compared with healthy controls; uptake of these EV can induce human pulmonary vascular endothelial cell death." (PMID 35234046, 2022).